IL10 (interleukin 10)
Diseases named in the same sentence as IL10 in open-access papers (continued):
Sharing a sentence is not in itself a finding about the gene and the disease.
Allergy (continued). "Inhibiting IL-4 has been associated with alleviating allergies while the neutralization of IL-10 has been linked to the reduction of helminth infection by restoring the function of Th2 effector cells." (PMID 25705127, 2015). "Levels of CD4+ IFN-γ+ (Th1), IL-13+ (allergy-associated Th2), as well as IL-17+ and IL-10+ (immunoregulatory) cells peaked at 72 hours in mice exposed to WT conidia and indicated a mixed Th1, Th2 and Th17 response." (PMID 25340353, 2014). "The levels of pro-inflammatory cytokines (IL-1β, IL-6, TNF), anti-inflammatory cytokine (IL-10), Th2-type cytokines associated with allergy (IL-4, IL-13, IL-33) and Th1-type cytokine (IFN-γ) were analysed from the treated skin sites of all groups." (PMID 25123235, 2014). "Interleukin (IL)-10 is a pleiotropic, immunoregulatory cytokine that is important in protecting the host from infection-associated immunopathology, autoimmunity, and allergy." (PMID 23755052, 2013). "The IL-16/IL-10 ratios reflected sensitivity to allergy and were associated with S100B levels and oppositional symptoms." (PMID 20509936, 2010). "On the other hand, regarding allergic diseases, IL-10 was demonstrated in several studies to be associated with lower risk for atopy or sensitization to egg protein in later life." (PMID 16551363, 2006). "Some studies suggest that insufficient sleep can alter levels of inflammatory cytokines such as interleukin (IL)-1β, IL-4, IL-6, and IL-10, which may promote allergic reactions and elevate the risk of developing AR." (PMID 40283018, 2025). "Interestingly, the anti-inflammatory IL-10 and the allergy-associated cytokines, IL-9 and IL-13, were also significantly lower in FHL1−/− than WT mice at both time points." (PMID 37884534, 2023). "Moreover, mutations of IL10 that decrease IL-10 production are correlated with the incidence of allergy." (PMID 37947634, 2023). "Of note, increased secretion of IL-10 by Treg was associated with successful treatment of allergy." (PMID 36703968, 2022). "In addition to T cells, IL‐10‐secreting B (Br1) have been associated with protection against allergic diseases." (PMID 35734271, 2022). "Although CD40L secreted by exposure to Aspergillus spp causes an allergic reaction, it may eventually induce IL-10 secretion to suppress excessive immunity." (PMID 35628692, 2022). "The high production of fecal EDN, IL-1β, and IL-10 during the first weeks of life may therefore be an indicator for later risk of allergic diseases." (PMID 35628877, 2022). "Almost all cohorts investigated more than one area, although some were seemingly restricted to specific areas, such as the FONIA cohort study, which studied the association between allergen-induced IL-10 production by cord blood cells and prospective risk of allergy development." (PMID 34300152, 2021). "Numerous studies have shown that Treg cells as main producers of Transforming Growth Factor beta 1 (TGFβ1) and Interleukin 10 (IL-10) play an important role in protecting against allergic diseases, thus the alteration in Treg cells is associated with eosinophilic allergy." (PMID 33868606, 2021). "Previous studies indicate that reduced activity of regulatory T cells, such as IL-10-producing Tr1 cells or Foxp3+ Treg cells is associated with allergic disease and that allergen-specific immunotherapy might increase their activity." (PMID 32391011, 2020). "Moreover, the severity of allergic diseases and the susceptibility to helminth infection has been associated with some polymorphic forms of the IL-10 gene." (PMID 30713536, 2018). "Alveolar MØ from ovalbumin (OVA)-sensitized allergy-susceptible Brown Norway (BN) rats released more IL-10 than alveolar MØ from allergy-resistant Sprague Dawley (SD) rats 24 h after OVA challenge, and the transfer of alveolar MØ from SD rats to the BN rats suppressed the AHR." (PMID 25430775, 2015).
Allergy (continued). "Another consequence is that infections causing the expansion of interleukin-10-producing regulatory cells may have protective effects against allergic diseases." (PMID 26904722, 2013). "More specifically, exposure of DCs to elevated concentrations of 12,13-diHOME reduced their IL-10 production and the frequency of T-regulatory cells in coculture assays, implicating this lipid as a driver of early-life immune dysfunction underlying allergic disease development." (PMID 38974097, 2024). "Thus, severe allergy induced hyporesponsive TIGIT+ IL-10+ ILC2s similar to Cbfβ-deficient ILC2s." (PMID 30683858, 2019). "Since there was an elevated systemic IL-10-secreting Treg response in infected patients, we hypothesized that as in the mouse, this could be an important mechanism behind the protective associations with allergy." (PMID 27014260, 2016). "The effects of RosA on OVA challenge allergy in mice effectively improved the expression of anti‐inflammatory mediators, such as IL‐10 and forkhead box protein P3 (FOXP3)." (PMID 41523289, 2026). "The M2a subtype synthesizes cytokines such as IL-4, IL-10, and IL-13, playing a role in allergies, anti-inflammatory activity, and the induction of fibrosis." (PMID 41499529, 2026). "Probiotic supplementation with Escherichia coli EcO83 in newborns of allergic mothers reduced allergy incidence at 10 years, likely through immune modulation (increased IL-10, CD83 expression)." (PMID 41010534, 2025). "In a peanut/cholera toxin food allergy model, it has been shown that the production of IL-10 by T follicular regulatory cells enhances germinal center B cell levels and drives production of peanut-specific IgE." (PMID 40065718, 2025). "Allergy symptom scoring (gastrointestinal, respiratory, skin, and systemic allergy reflections); inflammatory factors (TNFα/IL-1β/IL-6/IL-10); antibodies (IgE/IgG2); efficacy in eczema reduction." (PMID 40529417, 2025). "If methylation in genes that control Treg function (e.g., FOXP3, IL-10, TGFβ1) increases, it can reduce gene activity, contributing to the development of allergies." (PMID 41176788, 2025). "In individuals with allergic diseases, however, Treg function is often compromised, with decreased production of anti-inflammatory cytokines like interleukin-10 (IL-10) and transforming growth factor beta (TGF-β)." (PMID 40431425, 2025). "Genetic polymorphisms in immune regulatory genes, such as IL10 and Toll-like receptor 7 (TLR7), have been implicated in modulating the Th1/Th2 balance and influencing susceptibility to allergic diseases." (PMID 41465112, 2025). "Recent studies highlight the role of IL-10-producing regulatory B cells (Bregs) in allergic diseases." (PMID 39806495, 2025). "Th2 cells play roles in both allergic disease development and immune regulation through IL-10 production." (PMID 40025135, 2025). "In the context of allergy treatment, elevated IL-10 levels are crucial for mediating allergy tolerance by regulating Th2-driven allergic diseases." (PMID 39729447, 2024). "Tregs, a source of IL-10, suppress allergies, but their accumulation in cancer tissue has been found to be associated with the disease progression." (PMID 38892863, 2024). "The lung OVA-specific cytokine panel was expanded to include two additional allergy related cytokines mediators (IL-10, IL-13) in addition to the previously evaluated Th1/2 cytokines." (PMID 39108263, 2024). "Similar genes and other mechanisms such as epithelial barrier damage, gut microbiota dysbiosis and reduced number of T regs and IL-10 contribute to the onset of allergy and autoimmunity." (PMID 38027278, 2023). "IL10 secreted from DCs is required for the development of IL10 producing T cells and has been found to promote individual’s outcomes during allergy immunotherapy." (PMID 38174112, 2023). "The current child’s weight was positively correlated with IL10 methylation level in patients with allergy (rho=0.203, p=0.017)." (PMID 37520545, 2023).
Allergy (continued). "The IL-10-dependent suppression of inflammation by B10 cells is well documented in adult mouse autoimmune, allergy and infection models." (PMID 36735294, 2023). "Here, we show that GJExCR treatment reduced the Th2-mediated immune response in OVA-induced allergy, including dampening of IL-4, IL-5, IL-10, IL-13, TNF-α, INF-γ, chemokine, and IgE expression, in both serum and spleens." (PMID 36980282, 2023). "This indicates that the upregulation of IL-10 in MSCs is useful for the treatment of allergic airway inflammation, providing new insights for cell-based therapeutic products in allergic diseases." (PMID 38093354, 2023). "In previous studies, exogenous IL-10 has been investigated as a potential therapeutic agent for allergic diseases in mouse models." (PMID 37275919, 2023). "Ablation of IL-10 signalling in Th2 cells enhanced Th2 cell survival and exacerbated pulmonary inflammation in a murine model of house dust mite allergy." (PMID 38093354, 2023). "IL-10 is an important regulatory cytokine that plays a critical role in the control of allergic diseases." (PMID 37275919, 2023). "Regarding regulatory CD4+ T cells, the severity of allergic reactions has been associated with functional damage of allergen-specific Treg cells (CXCR5-FoxP3+IL-10+), Tr-1 (CXCR5-FoxP3-IL-10+) and, mainly in IgE-mediated disorders, TFR (CXCR5+FoxP3+IL-10+)." (PMID 37954580, 2023). "Microorganisms modulate immune responses, including the production of cytokines such as IL-6 and IL-10, to affect the development of immune reactions and protection against allergic diseases." (PMID 37978564, 2023). "Interleukin-10 is a type of cytokine that has a role in allergic diseases by influencing various cell functions such as the activation of Th2 cells, the function of mast cells and eosinophils, and the ratio of IgG to IgE." (PMID 37760982, 2023). "Recent studies have shown that in chronic inflammatory conditions such as autoimmune and allergic diseases the number of circulating B regs and the production of IL10 are reduced." (PMID 38027278, 2023). "IL-10 production by Treg cells is critical for the control of immune response and increases allergy-induced lung inflammation and hyperreactivity in Il10flox/flox×Foxp3YFP-Cre mice." (PMID 36177049, 2022). "In PBMCs from infants with cow milk allergy and in the presence of bovine and caprine milk fractions, a high amount of IL-10 was detected as compared to healthy infants." (PMID 35684043, 2022). "In contrast, Th2 cells, which produce IL-4, IL-5, IL-6, IL-9, IL-10, and IL-13, induce strong antibody responses by B cells, induce eosinophil activation, and are responsible for allergic reactions." (PMID 35646978, 2022). "The critical role of IL-10 in preventing allergic diseases and limiting the clinical signs of allergic disease manifestation has been acknowledged." (PMID 36703968, 2022). "Th2 cells can secrete IL-3, IL-4, IL-5, IL-10, and IL-13, and these cells can thereby mediate B-cell differentiation through IL-4, participate in allergic reactions and mediate macrophage deactivation through IL-4, IL-10 and IL-13." (PMID 36225183, 2022). "The generation and maintenance of Treg cells and their suppressive cytokines (TGF-β, IL-10) are essential for the induction of allergen tolerance in allergic disease." (PMID 35211018, 2022). "IL10 is multiple-functional cytokine during allergic symptoms and a significant element in the progression of severe allergic diseases, including AD, AR, and AA." (PMID 35678682, 2022). "Similar to the allergy model, CCR4 inhibition resulted in a reduction of Th2/Th17-associated cytokines, while the levels of IL-10 were increased." (PMID 33669094, 2021). "Some peptides like GYLEQLLRLKKYKVPQLEIVPNSA, and QKHIQKEDVPSERYLGYLEQLLRL of Bos d9, despite its potential to induce interleukin 10 expression, show a theoretical strong potential to induce allergies." (PMID 33466712, 2021).
Allergy (continued). "In this review, the molecular mechanisms regulating IL-10 production in NK cells and ILC2s are discussed in details for the first time, and the role of IL-10-producing ILCs in diseases such as infections, allergies, and cancers are summarized." (PMID 33859642, 2021). "In contrast, Th2 cytokines produce the cytokines IL-4, IL-10, and IL-13, which stimulate the production of antibodies directed toward large extracellular parasites, including allergies." (PMID 34945585, 2021). "Neonatal therapy with E. coli O83:K24:H31 reduces allergy rates, augments T regulatory cells and elevates their IL-10 expression, as well as raising serum IL-10 and IFN-γ levels in children." (PMID 34360926, 2021). "When aimed specifically to address types of inflammation in mice, allergy (anaphylaxis) induced IL-10 and a corresponding response, while lipopolysaccharide stimulated various types of cells including WBCs to induce the release of a series of active molecules." (PMID 34856939, 2021). "In the context of clinical allergy, repeated exposure to certain allergens promote a “modified allergy” milieu in which Th2-derived IL-4 and Treg-derived IL-10 combine to induce IgG4 production." (PMID 34305927, 2021). "The other anti-inflammatory factor, IL-10, is the main cytokine produced by Treg cells in allergic diseases." (PMID 34880869, 2021). "Meanwhile, the reduction of airway responsiveness and IgE production dependent on IL10 was also evident in the mice model for allergic disease, showing the immunoregulatory function of IL10." (PMID 33673676, 2021). "These cells produce cytokines characteristic of the Th1-dependent response (IL-2, IFN-γ) and Th2 cells (IL-4, IL-5, IL-10) so they can play both protective and pathogenetic roles in allergic diseases, depending on the disease phase." (PMID 33435598, 2021). "High levels of IL-10 transcripts in T cells of patients with HDM allergy predicted the success of AIT." (PMID 35387059, 2021). "Oral administration of L. reuterii, a gram-positive bacterium similar to FP, in a mouse allergy model has been reported to decrease Il4 and Ifng, and increase Il10 mRNA expression in the spleen." (PMID 32184789, 2020). "Regulatory T cell-derived IL-10 was previously reported to be responsible for the immunosuppression of allergy-related cells." (PMID 32120968, 2020). "It is known that Foxp3 and IL-10 play a key role in allergy suppression and maintaining immune tolerance." (PMID 33679699, 2020). "Levels of allergy mediating cytokines, IL-6, IL-10, and IFN-γ, as well as chemokines RANTES and TARC were also reduced upon SHE administration." (PMID 32824648, 2020). "IL-10–dependent prevention of allergy has also been observed with the parasite N. brasiliensis, in a model of OVA-induced airway hyperresponsiveness in rats." (PMID 33013887, 2020). "Transforming growth factor-β (TGF-β) and IL-10 are Treg-related cytokines that are essential for maintaining immune tolerance and reducing allergic reactions." (PMID 32957487, 2020). "An increased concentration of IgG4 Abs, IL-10 and other regulatory cytokines induced by helminth infections seem to play an important role in the suppression of allergic diseases in humans." (PMID 32268573, 2020). "Together, these reports emphasize the need for well-controlled experiments that will sort out exactly how IL-10, and more specifically IgE-binding monocytes, contribute to allergic disease or allergen tolerance in the context of specific allergen stimulation." (PMID 32442209, 2020). "In contrast, Th2 cells mainly secrete IL-4, IL-3, IL-6, and IL-10 to stimulate the proliferation of activated B cells, to produce antibodies, and to participate in humoral immune-related or allergic diseases." (PMID 33659270, 2020). "Over the last decade, the anti-inflammatory cytokine IL-10, mainly produced by Tregs, has been under the spotlight in regards to its role in a variety of allergic diseases." (PMID 32194407, 2020).
Allergy (continued). "Th2 cells are the main T cell subsets involved in allergic diseases, which release effector cytokines, such as IL-4, IL-10, and IL-13, that will interact with B cells for the synthesis of allergen-specific IgE." (PMID 33224143, 2020). "IL-10 enhances IgE-mediated mast cell responses and is necessary mediator of allergy development in vivo." (PMID 31429774, 2019). "TLR5-dependent IL-10 secretion has also been described as part of the response to a flagellin fusion protein studied to prevent allergy; our findings are consistent with this observation." (PMID 31776239, 2019). "This seems to be in contrast with the observed allergy protection, since IL-10 is known as a regulatory cytokine." (PMID 31349704, 2019). "A higher in vitro production of IL-10 by splenocytes, regulatory cytokine playing an important role in suppressing allergy responses, was also found." (PMID 30813365, 2019). "The previous result indicated that S. cerevisiae was able to restore IL-10 level in the prevention of allergic diseases for mice, corresponding with this study." (PMID 31482249, 2019). "IL10 directed immunotherapy, on the other hand has the potential to be incompletely allergen specific and favor the resolution of combinations of allergies." (PMID 29164823, 2018). "The analysis of serum cytokines showed that piglets with FOS supplementation had higher interferon-γ level, but lower levels of IL-4 and IL-10 compared with the allergy group." (PMID 30524396, 2018). "Microbes in the allergy group were correlated positively to specific IgG, IL-4, and IL-10 and were correlated negatively to IFN-γ." (PMID 30524396, 2018). "Here, combining the presentation of allergens by DCs with a pro-tolerogenic, IL-10-producing phenotype is of special interest to modulate allergen-specific immune responses in the treatment of allergic diseases." (PMID 29616018, 2018). "IL-10 modulates the activity of numerous cells involved in allergic diseases, mast cells, Th2 cells, and eosinophils." (PMID 30013991, 2018). "A recent study analyzed the effect of IL-10-treated bone marrow-derived cells (BMDC) in a Th2 model of allergy using aluminum hydroxide adsorbed OVA for sensitization of BALB/c mice." (PMID 29751492, 2018). "Up to now, numerous studies support the importance of IL-10 produced by either Treg or Tr1 cells, IL-10-producing regulatory B cells, and lung DCs in the modulation of allergic diseases." (PMID 29616018, 2018). "Recent studies suggest that naturally occurring Treg cells and antigen-induced IL-10-producing Treg cells play a role in protecting against human allergic disease." (PMID 29751492, 2018). "This makes IL-10-producing DCs promising therapeutics to improve the treatment of allergic diseases." (PMID 29616018, 2018). "The role of altered Treg cell production of IL-10 and TGF-β in the pathogenesis of allergic diseases and the underlying mechanisms for such alterations remain to be fully elucidated." (PMID 29375821, 2018). "Tregs36 and Bregs37 as sources of immunomodulatory cytokines IL-10 and TGFb counterregulate the Th2 cytokine dominance in allergy, including the Th2 cytokine IL-5." (PMID 28566688, 2017). "We then tested if Gal1 reversed the ability of IL-10 expression in allergy mouse-derived CD14+ cells." (PMID 28086216, 2017). "The production of IL-10 by B10 cells in response to allergens plays a pivotal role in allergy inhibition." (PMID 28428801, 2017). "Both human and murine B10 cells have been shown to produce large amounts of IL-10 and to exert an inhibitory effect on allergy development." (PMID 28428801, 2017). "Although more investigation is needed, the iTregs with IL-10-mediated suppressive action represent promising targets for future allergy therapies, and potential efficacy biomarker for novel types of allergen-specific immunotherapy and cell-based therapies." (PMID 28931869, 2017). "The requirement for the release of IL-10 by Tregs in the control of allergic reactions has been demonstrated." (PMID 28589115, 2017).